DES (desmin)
Diseases named in the same sentence as DES in open-access papers (continued):
Sharing a sentence is not in itself a finding about the gene and the disease.
desminopathies (68 papers, 2013 to 2025). "Our data show that TANGO2 is required for CRYAB activity and intermediate filament structure as its loss leads to a desminopathy that is consistent with those identified in patients carrying desmin and CRYAB mutations." (PMID 40480980, 2025). "These cases were confirmed by cytoplasmic desmin-positive immunoreactivity, a hallmark of desminopathy." (PMID 40574817, 2025). "Desminopathies, stemming from mutations in the desmin-encoding gene (DES), present with progressive bilateral distal muscle weakness that progresses to affect proximal muscles, accompanied by respiratory distress and cardiomyopathy." (PMID 40268053, 2025). "Desminopathies can arise from mutations within desmin itself, and several pathogenic desmin mutations have been described; however, they can also arise from the dysfunction of proteins involved in protein folding and stability." (PMID 38474073, 2024). "Genetic analyses revealed a desminopathy caused by mutation of the gene coding for desmin -DES gene- located on chromosome 2 (c.1315G > A (p.Glu439Lys)." (PMID 38811883, 2024). "Mutations in desmin are associated with desmin-related (cardio)myopathy, which is also known as desminopathy." (PMID 36628457, 2023). "In our case, the diagnosis of desminopathy was strongly suggested by the MB, which revealed the presence of some abnormal desmin aggregates, a typical clue of patients with DES variants, and then confirmed by genetic testing." (PMID 37240454, 2023). "This pathologic pattern is seen in one mouse and two rat desminopathy-related models, and in patients with desmin mutations, and its significance in an experimental PH study needs to be further explored." (PMID 36142826, 2022). "Mutations in desmin cause a variety of skeletal and cardiac myopathies, called desminopathies, which are characterized by toxic aggregation of mutant misfolded desmin." (PMID 33467597, 2021). "More than 70 mutations in the desmin gene have been associated with desminopathies, and six of them (Ser12Phe, Ser13Phe, Arg16Cys, Ala285Val, Ser298Leu, Asp312Asn) are located within the NLSs on desmin." (PMID 35068951, 2021). "Here, we provide new insights into (i) the connection of mutated desmin to axial active/passive biomechanics in single fibers and (ii) the age-dependent progression of altered fiber mechanics in the R349P desminopathy model." (PMID 32752098, 2020). "Desminopathies in humans, caused by desmin and other gene mutations with a loss of desmin function, is a group of myofibrillar myopathies." (PMID 32708381, 2020). "Desminopathy (OMIM # 601409) represents a group of autosomal inherited disorders caused by pathogenic variants in the disease-causing desmin (DES) gene, encoding the major muscle specific intermediate filament protein desmin (OMIM: #125660)." (PMID 32235386, 2020). "This diagnosis was reclassified to desminopathy after the identification of known pathogenic desmin mutation (p.(R454W)) and morphological analysis of myocardial samples from the explanted heart." (PMID 32235386, 2020). "Desminopathy is a clinically heterogeneous muscle disease caused by over 60 different mutations in desmin." (PMID 32893996, 2020). "Desminopathies or desmin‐related myopathies are a clinically heterogeneous group of myofibrillar myopathies caused by mutations of the desmin gene or its interactive partners." (PMID 32893996, 2020). "To overcome these limitations, we generated the patient-mimicking R349P desmin knock-in desminopathy mouse model, which harbors the orthologs of the most frequent human desmin mutation R350P." (PMID 32752098, 2020). "Mutations that cause desminopathies illustrate that Desmin is essential to maintain sarcomere integrity." (PMID 31612857, 2019). "Desminopathy belongs to a genetically heterogeneous group of disorders named myofibrillar myopathy, caused by mutations in desmin, αB-crystallin, myotilin, Z-band alternatively spliced PDZ-containing protein, filamin, or Bcl-2-associated athanogene." (PMID 30841624, 2019).
desminopathies (continued). "Mutations of desmin are associated with desminopathy, and this protein is found to be enriched in aggregate-associated tissues in myotilinopathy, filaminopathy and IBM." (PMID 31796104, 2019). "These cells also exhibited high levels of α-crystallin B chain (CRYAB), a stress-associated chaperone that stabilizes desmin (a DUX4c partner,) and thus maintains intermediate filament integrity; this chaperone is up-regulated in desminopathies as well." (PMID 29329560, 2018). "Two desmin mutants located in the C-terminal tail domain that cause desminopathy (I451M and R454W) were then assessed for their CRYAB binding." (PMID 28470624, 2017). "Desminopathy caused by R454W desmin mutation is associated with disintegrated Z-discs and severe misalignment of myofibrils." (PMID 28470624, 2017). "A key finding of this study was that mutant desmin linked to desminopathy changed the desmin filament topology, and that it significantly altered its binding affinity to CRYAB." (PMID 28470624, 2017). "It has also been shown that cardiac-specific expression of CryABR120G, a mismatch mutant genetically associated with human desmin-related cardiomyopathy (also known as desminopathy), results in abnormal desmin aggregation and heart failure in mice." (PMID 29088822, 2017). "In this study, we have successfully constructed desminopathy disease animal model by direct intramuscular transduction with adenovirus coding mutations of the gene desmin, the high stability of the model was validated." (PMID 27941998, 2016). "Desminopathies caused by the mutation in the gene coding for desmin are genetically protein aggregation myopathies." (PMID 27941998, 2016). "In this study, desminopathy model was constructed by direct intramuscular transduction with the adenoviral vector containing mutations of desmin(c.821T> C; L274P)." (PMID 27941998, 2016). "In the previous study, Pierre Joanne constructed desminopathy model by direct intramuscular transduction with the protein of the mutant desmin coated adeno-associated virus." (PMID 27941998, 2016). "To address this issue in a mechanistic perspective, we analyzed skeletal muscle tissue specimens derived from the R349P desmin knock-in mice and human desminopathy patients harboring heterozygous DES mutations." (PMID 27393313, 2016). "Desmin-positive protein aggregates are the morphological hallmark of desminopathies and all other MFMs." (PMID 25394388, 2015). "Among several post-translational modifications, desmin was demonstrated to be a major target of oxidation and nitration in both desminopathies and myotilinopathies, characterized by mutation of desmin and myotilin, respectively." (PMID 26333167, 2015). "One intriguing feature of MFMs resulting from mutations in desmin (also called desminopathies) is the adult onset of their progressive muscle phenotype, mainly between the second and fourth decade of life." (PMID 26333167, 2015). "Because NAC is an approved drug, it warrants further investigation in animal models as AAV-desmin-expression model developed in our laboratory to determine its value in delaying the onset of DesD399Y-linked desminopathies." (PMID 24098483, 2013). "In the desminopathy meta-analysis, however, a mortality rate of 26 % (27/104) of desmin mutation carriers with a mean age 49 ± 9.3 years was reported." (PMID 23143191, 2013). "Studies on desmin protein expression in desminopathies due to deletion or frame-shift mutations would allow at least the determination of the expression level of the mutant desmin species." (PMID 23143191, 2013).
desminopathies (continued). "In a desminopathy due to the heterozygous p.Lys240del mutation, an aberrant and more acidic spectrum of desmin spots was visible, whereas the p.Asp214_Glu245del desmin mutant species presented with a more alkaline pI." (PMID 23143191, 2013). "Mutations within the human desmin gene are responsible for a subcategory of myofibrillar myopathies called desminopathies." (PMID 24098483, 2013). "Variants in the desmin gene (DES) are associated with desminopathy; a myofibrillar myopathy mainly characterized by muscle weakness, conduction block, and dilated cardiomyopathy." (PMID 23815709, 2013). "In another study on a desminopathy due to a heterozygous c.735G>C mutation, desmin immunoblotting revealed the presence of two bands at the positions of 53 kDa and 50 kDa." (PMID 23143191, 2013). "Among these, desminopathy, a rare inherited myopathy, is caused by pathogenic variants in the desmin gene (DES), leading to progressive skeletal muscle weakness and a range of cardiac manifestations, including cardiac conduction disorders, arrhythmias, and cardiomyopathy." (PMID 40529556, 2025). "Additionally, these models of desminopathies stimulate the localized loss and aggregation of desmin throughout the myofiber." (PMID 38824194, 2024). "Indeed, desminopathies are inherited disorders that result from mutations of the desmin (DES) genes, leading to the accumulation of aggregates of misfolded desmin." (PMID 35625721, 2022). "Mutations in the desmin gene causes skeletal and cardiac myopathies known as desminopathies." (PMID 35068951, 2021). "Transgenic overexpression of αB-crystallin was effective in restoring mitochondrial quality and rescuing cardiac myocytes death in mice with genetic ablation of desmin, a mouse model for desminopathies that result from loss of function of desmin due to genetic mutations." (PMID 32581848, 2020). "Moreover, apoptosis related protein are also associated with desmin mutation in the patients with desminopathies or rat desminopathies model." (PMID 27941998, 2016). "Hence, our data demonstrate that the expression of mutant desmin causes multi-level damage of mitochondria already in early stages of desminopathies." (PMID 27393313, 2016). "In the desminopathy patient, approximately 20 % of total desmin protein is the mutant variant." (PMID 25394388, 2015). "Desmin-positive protein aggregates, the morphological hallmark of desminopathies and all other forms of MFMs, were present in both HET and HOM mice, but clear evidence of progressive skeletal muscle weakness and morphological signs of myopathic alterations was only present in the latter." (PMID 25394388, 2015). "Together, these data suggest that desminopathies may occur via two distinct molecular mechanisms: dominant-negative effects exerted by mutant desmin proteins and complete loss of the desmin protein." (PMID 23815709, 2013). "With regard to a putative mitochondrial pathology, an analysis of the mitochondrial function in isolated saponin-permeablized skeletal muscle fibres from a desminopathy patient (heterozygous p.Lys240del desmin mutation) revealed an in vivo inhibition of complex I activity." (PMID 23143191, 2013). "desminopathies) could result from mutation in the desmin gene, cleavage of desmin, and/or changes on post-translational modifications, leading to an altered desmin network and the formation of toxic desmin aggregates." (PMID 35701470, 2022). "Desminopathies, a subgroup of myofibrillar myopathies (MFMs), the progressive muscular diseases characterized by the accumulation of granulofilamentous desmin-positive aggregates, result from mutations in the desmin gene (DES), encoding a muscle-specific intermediate filament." (PMID 26333167, 2015). "Autosomal‐dominant forms, by far the most frequent form of human desminopathies, typically display desmin‐positive protein aggregation pathology and myofibrillar disarray in striated muscle tissue." (PMID 41165044, 2025).
desminopathies (continued). "In the present work, we investigated the effects of the mixed expression of R349P and wild‐type desmin, as well as the sole expression of R349P desmin, on the proteomic profiles in all skeletal muscle fiber types of the R349P desminopathy mouse model." (PMID 40033788, 2025). "Desminopathies are inherited myofibrillar myopathies caused by pathogenic variants in the DES gene, encoding desmin, a key intermediate filament protein in skeletal and cardiac muscle." (PMID 41463072, 2025). "A subset of desminopathies, alpha-B crystallinopathies, results from mutations in CRYAB-encoding alpha B-crystallin, a desmin-stabilizing chaperone protein." (PMID 40268053, 2025). "We analysed heterozygous and homozygous R349P desmin knock‐in mice and R405W desmin knock‐in mice, which serve as disease models for the human R350P and R406W desminopathies, respectively." (PMID 40947309, 2025). "In line with previous results from the analysis of desmin knock‐out mice, measurement of blood acylcarnitine levels appears to be of potential clinical interest in the context of recessive desminopathies." (PMID 41165044, 2025). "Using R349P‐desmin knock‐in mice, a model for the human R350P desminopathy, strenuous treadmill exercise was found to lead to a significant increase in xirp 1/2‐positive sarcomeric lesions in the soleus muscle." (PMID 40947309, 2025). "This problem is associated with a structurally and functionally compromised extrasarcomeric desmin cytoskeleton in the desminopathy animals." (PMID 40947309, 2025). "The term ‘desminopathies’ comprises all DES mutation‐related disorders irrespective of their form of inheritance, mutation type and their consequences on desmin protein expression." (PMID 41165044, 2025). "These desminopathy mice develop a desmin‐positive protein aggregation pathology, skeletal muscle weakness, dilated cardiomyopathy, as well as cardiac arrhythmias and conduction defects." (PMID 40033788, 2025). "Pathologies arising from desmin-related dysfunction and aggregation are termed desminopathies, and when they involve muscle tissue, they are named desmin-related myopathies." (PMID 38474073, 2024). "The upregulated cell migration, adhesion process, and ECM found in our desminopathy patients is likely to be a compensatory mechanism of the defective desmin." (PMID 39239540, 2024). "A small number of hiPSC lines have been created from patients with desmin-related CMPs (a subtype of desminopathies)." (PMID 37895213, 2023). "We report three desminopathy cases which highlight the phenotypic heterogeneity of this disorder and discuss various factors that may contribute to the clinical differences seen between patients with different desmin variants and also between family members with the same variant." (PMID 36726751, 2023). "Moreover, oxidized desmin is more susceptible to cleavage, which could contribute to muscle waste, and is potentially also more prone to aggregate, since N-acetyl cysteine prevents stress-induced desmin aggregation in several models of desminopathies." (PMID 37760006, 2023). "This new role of desmin opens avenues of investigation into the physiology and pathology of desminopathies, potentially leading to the identification of new therapeutic targets for these currently incurable diseases." (PMID 35350386, 2022). "In desminopathies, desmin aggregates are characteristic of the pathology; however, these aggregates remain heterogeneously distributed within the cardiac or skeletal muscle tissues." (PMID 36453730, 2022). "The severe cardiac disease outcomes emphasize the clinical need to understand the molecular and cellular role of desmin driving desminopathies." (PMID 36158202, 2022). "Findings in patients and in desmin knock-out mice indicate that the key process in the molecular pathogenesis of this very rare desminopathy subform is generalized destabilization of the extrasarcomeric cytoskeleton due to the lack of its major component." (PMID 36233322, 2022).
desminopathies (continued). "Cardiac-specific overexpression of alpha-B crystallin in this mouse model provided a clear demonstration of the involvement of mitochondrial disfunction in desminopathy and of the role of the desmin chaperone." (PMID 33923914, 2021). "Abundant accumulation of desmin-immunoreactive deposits and granulofilamentous material at the ultrastructural level are considered morphological hallmarks of desminopathy." (PMID 33923914, 2021). "Mutations in the desmin gene (DES) cause skeletal and cardiac myopathies, collectively known as desminopathies." (PMID 35068951, 2021). "In desminopathies and desmin-null mice, it has been shown that cardiomyocyte death activates an inflammatory pathway and causes secretion of pro-inflammatory molecules." (PMID 33923914, 2021). "Potential treatments for desminopathy have been explored by testing drugs that avoid desmin aggregate formation as antioxidants and stimulators of macroautophagy." (PMID 33923914, 2021). "It was therefore suggested that these aggregates were a direct result of a ‘final common pathway’ disturbance of the interplay between desmosomal proteins and desmin, with the final phenotype consistent with a desminopathy." (PMID 33605084, 2021). "Our experiments on single muscle fibers, void of ECM, suggest that compromised biomechanics properties in the R349P desminopathy do not only originate from increased fibrosis, but also from mutant desmin inflicted damage to the cytoskeleton." (PMID 32752098, 2020). "The changes in desmin expression were described in the context of the so-called desminopathies, which impair the cardiac mechanical properties as well as the calcium homeostasis." (PMID 32584885, 2020). "Desminopathy caused by a single nucleotide polymorphism in the DES gene that converts arginine 350 to proline (R350P), the most prevalent mutation of desmin in humans, commonly presents as progressive muscular atrophy and muscle weakness." (PMID 32893996, 2020). "Our previous analyses of R349P desmin knock-in mice, an animal model for the human R350P desminopathy, already depicted pre-clinical changes in myofibrillar arrangement and increased fiber bundle stiffness." (PMID 32752098, 2020). "A subgroup of human desminopathies comprises autosomal recessive cases resulting in the complete abolition of desmin protein." (PMID 33192292, 2020). "Desminopathies are clinically defined as a myofibrillar myopathy characterized by desmin positive protein aggregates and degenerative changes to contractile fibres." (PMID 32893996, 2020). "Since studies on desmin-related cardiac pathology are generally hampered by virtual absence of respective human tissue specimens, animal models for human desminopathies are valuable tools for molecular analysis and therapeutic treatment studies." (PMID 32322014, 2019). "As a surrogate for autosomal-recessive desminopathies with maintained desmin protein expression and the presence of protein aggregation we used homozygous R349P DKI mice as a model." (PMID 32322014, 2019). "Dysfunction of the desmin network owing to mutations in the desmin gene or post-translational modifications leads to cardiac and skeletal myopathies, jointly called desmin-related myopathies or desminopathies." (PMID 31835587, 2019). "In the present study, we focused on the therapeutic effect of a high-dose AAV9-mediated expression of wild-type (WT) desmin on the cardiac pathology in two autosomal-recessive desminopathy subforms." (PMID 32322014, 2019). "The immunohistochemistry and EM of cardiac muscles from the homozygous desL114F/L114F KI mice showed desmin aggregates and granulofilamentous electron-dense materials, typical features of desminopathy." (PMID 31835587, 2019). "Aim of our study was to investigate the long-term therapeutic effects of AAV-mediated expression of WT desmin on the cardiac pathology in two desminopathy mouse models that were exposed to strenuous exercise." (PMID 32322014, 2019).